METTL3 (methyltransferase 3, N6-adenosine-methyltransferase complex catalytic subunit)
Diseases named in the same sentence as METTL3 in open-access papers (continued):
Sharing a sentence is not in itself a finding about the gene and the disease.
glioma (continued). "Our data showed that HOTAIRM1, post-transcriptionally stabilized by METTL3, bound to IGFBP2, suggesting that HOTAIRM1 promotes VM formation in glioma via up-regulating IGFBP2 expression, providing a theoretical basis for new glioma treatment methods." (PMID 38012763, 2023). "Recent studies have shown that METTL3 recognized by YTHDF2 mediates m6A modification to activate NF-κB and promote the malignant progression of glioma." (PMID 37759870, 2023). "For example, METTL3, FTO, and YTHDC1 are significantly differentially expressed between IDH-mutant and IDH-wildtype high grade gliomas." (PMID 38071304, 2023). "Interestingly, subsequent research has demonstrated that HuR is necessary for the METTL3-mediated stabilisation of metastasis-associated lung adenocarcinoma transcript 1 (MALAT1), which in turn activates nuclear factor kappa B (NFB) in isocitrate dehydrogenase (IDH) wildtype glioma." (PMID 37444417, 2023). "Another study indicated that YTHDF2 expression was positively associated with higher malignant grade, a molecular subtype of glioma, and poorer prognosis, and accelerated UBXN1 mRNA degradation via METTL3-mediated m6A; this in turn promoted NF-κB activation." (PMID 37189411, 2023). "Like what was observedin the context of CRC, METTL3 was foundto target SOX2 and consequently support the maintenance of highlytumorigenic glioma stem-like cells (GSCs) and the de-differentiationof glioma cells." (PMID 36692498, 2023). "HOTAIRM1, post-transcriptionally stabilized by METTL3, promotes VM formation in glioma via up-regulating IGFBP2 expression, which provides a new direction for glioma therapy." (PMID 38012763, 2023). "METTL3 was found to post-transcriptionally stabilized HOTAIRM1 and positively regulated its expression in glioma cells." (PMID 38012763, 2023). "METTL3 can regulate MALAT1 stabilization through m6A modification, and it activates NF-κB activity to promote the malignant progression of glioma." (PMID 35012593, 2022). "Similar to METTL3, the expression of YTHDF2 was significantly lower in differentiated glioma cells than in undifferentiated GSCs." (PMID 35682599, 2022). "This study elucidated that METTL3-mediated circDLC1 promoted CTNNBIP1 transcription by sponging miR-671-5p, thus repressing the malignant proliferation of glioma cells." (PMID 35474040, 2022). "It has been shown that both METTL3 and METTL14 contribute to the development and tumorigenesis of human glioma stem cells (GSCs), and METTL3 overexpression or suppression of FTO inhibits GSC self-renewal and growth." (PMID 35711459, 2022). "GEPIA and Wang database analysis showed a significant positive correlation between the expression of the m6A methyltransferases METTL3 and WEE2-AS1 in glioma tissues." (PMID 36168628, 2022). "The downregulation of METTL3 reduced the methylation of COL4A1 (Collagen type IV alpha 1) and increased its expression level, which promoted the proliferation and migration of glioma cells." (PMID 35682599, 2022). "Knockdown and overexpression were used to evaluate the effects of YTHDF2, methyltransferase-like 3 (METTL3), and UBX domain protein 1 (UBXN1) on glioma malignancy in cell and orthotopic xenograft models." (PMID 34246306, 2021). "Previous studies have shown that the m6A RNA methylase METTL3 promotes glioma progression by stabilizing the expression of SOX2, suggesting an important role of m6A modifications in glioma." (PMID 34803608, 2021). "METTL3 enhances the m6A methylation by improving the stability of SOX2 in GBM, thereby promoting the stemness of glioma stem cells (GSCs)." (PMID 34336690, 2021). "For glioma, we found that IGF2BP2, KIAA1429, METTL16, METTL3, and YTHDF1 are consistently upregulated at the mRNA level of CGGA and GSE16011 datasets (7.97E-05 < FDR < 0.04)." (PMID 34589481, 2021). "We decreased VPS25 expression in METTL3, METTL14, and YTHDC1 KD glioma cells, and a series of restoration assays were performed." (PMID 34863175, 2021).
glioma (continued). "Our study firstly established a seven-gene signature comprising METTL3, COL18A1, NASP, PHLPP2, TIMP1, U2AF2, and VEGFA with a good capability for predicting survival in glioma." (PMID 34589481, 2021). "Similar to METTL3, YTHDF2 expression is also decreased in differentiated glioma cells compared with GSCs." (PMID 34246306, 2021). "The integrated analysis of the m6A regulome in METTL3-silenced GSCs showed global disruption in tumorigenic pathways that are indispensable for GSC maintenance and glioma progression." (PMID 30781903, 2019). "METTL3-mediated m6A modification is proposed to play a crucial role in glioma stem-like cell (GSC) maintenance and dedifferentiation of glioma cells, based on the finding that expression of METTL3 is elevated in GSCs and attenuated in differentiated cells." (PMID 29439529, 2018). "Furthermore, METTL3 suppresses MIF expression by upregulating EIF3J-AS1, thereby inhibiting autophagy in glioma cells." (PMID 41390674, 2025). "METTL3-mediated m6A modification promotes GSC proliferation, self-renewal, and tumorigenesis, promoting cancer stem cell maintenance and dedifferentiation of glioma cells." (PMID 41321637, 2025). "After METTL3 knockdown, ADAM19 expression increases, which promotes the occurrence of glioma." (PMID 40469294, 2025). "The specific mechanism involves METTL3 stabilizing the mRNAs of BUD13 and CDK12, leading to their overexpression, which in turn promotes the phosphorylation of MBNL1 and facilitates the VM process in gliomas." (PMID 40469294, 2025). "Moreover, the upregulation of SOX2 mediated by METTL3 and the increased expression of ALKBH5 also enhance the radioresistance of glioma." (PMID 40469294, 2025). "Here, we found METTL3 is upregulated in high-grade glioma samples compared to non-tumor brain samples and low-grade glioma samples." (PMID 41321637, 2025). "Interestingly, ALKBH5 can also enhance glioma resistance to TMZ by stimulating the expression of SOX2, which coincides with the role of METTL3 in stabilizing GSCs through the promotion of SOX2 expression." (PMID 40469294, 2025). "Furthermore, we observed a significant colocalization between METTL3 and LINC00475-S in glioma tissues." (PMID 38405130, 2024). "Furthermore, overexpression of METTL3 up-regulated DRP1 and p-DRP1 proteins in both glioma cell cytoplasm and mitochondria while down-regulating OPA1 and MFN2 proteins." (PMID 38405130, 2024). "Additionally, METTL3-induced m6A methylation of LINC01003 was found to regulate the focal adhesion kinase (FAK) pathway, promoting glioma cell proliferation and migration." (PMID 38474421, 2024). "METTL3-mediated m6A modification, with the assistance of HuR, enhances the stability of MALAT1 and activates NF-κB, promoting the malignant progression of IDH wild-type glioma." (PMID 37964279, 2023). "The same study found that METTL3 expression is positively associated with a higher grade and poorer prognosis in IDH-wildtype glioma, but not in IDH-mutant gliomas." (PMID 37444417, 2023). "Moreover, the upregulation of METTL3 induced by fear stress stabilizes FSP1 mRNA through m6A modification, which leads to glioma progression by inhibition of ferroptosis." (PMID 37714846, 2023). "For example, METTL3 potentiates the stability of MALAT1 by m6A modification with the assistance of an RNA-binding protein, HuR, thereby facilitating the malignant progression in gliomas with IDH wild-type." (PMID 37927399, 2023). "METTL3 can also regulate the nonsense-mediated mRNA decay (NMD) pathway by increasing m6A methylation levels of serine- and arginine-rich splicing factors (SRSF) to promote glioma growth and invasion." (PMID 38072944, 2023).
glioma (continued). "Interestingly, compared to METTL3, METTL14 demonstrates more pronounced effects and primarily acts as an inhibitor of glioma progression, offering a novel avenue for therapeutic interventions in this disease." (PMID 37964279, 2023). "METTL3 expression can enhance the stability of MALAT1 through the m6A methylation, subsequently activating the nuclear factor kappa-B (NF-κB) signaling, thus facilitating the malignant progression of IDH-WT glioma." (PMID 38072944, 2023). "METTL3 silencing reduced the expression of the glioma reprogramming factors POU3F2, SOX2, SALL2 and OLIG2, and suppressed GSC proliferation in neurosphere assays derived from human glioma cell lines." (PMID 37444417, 2023). "Upon fear of stress, METTL3 upregulation could enhance the FSP1 stability, resulting in glioma progression and ferroptosis resistance." (PMID 37211949, 2023). "According to these findings, RP2 may be correlated with m6A modification in glioma, and the combined effect of METTL14, VIRMA, ALKBH5, YTHDC2 and METTL3 may eventually affect the progression and poor prognosis of glioma." (PMID 37602882, 2023). "Expression of the m6A ‘writer’ METTL3 was positively associated with a higher malignant grade and poorer prognosis of IDH-wildtype but not IDH-mutant gliomas." (PMID 36831575, 2023). "METTL3 promoted the stability of MALAT1 and enhanced the glioma progression." (PMID 36212476, 2022). "The study confirmed that METTL3 facilitates mRNA methylation, increases the stability of SRY transcription factor 2 (SOX2), improves SOX2 protein expression, and contributes to the radiation resistance and maintenance of glioma stem cell-like cells." (PMID 35711459, 2022). "Collectively, METTL3-mediated m6A modification upregulated circDLC1 expression, and circDLC1 promoted CTNNBIP1 transcription by sponging miR-671-5p, thus repressing the malignant proliferation of glioma." (PMID 35474040, 2022). "The mRNA level of VPS25 was upregulated in glioma cells with KD of METTL3 or METTL14, but it was not affected in the YTHDC1 KD cells." (PMID 34863175, 2021). "METTL3 was positively associated with DLL3, HES1, and NOTCH3 expressions in the CGGA glioma dataset, but not the GSE16011 glioma dataset (0.23 < cor < 0.34, p < 0.05)." (PMID 34589481, 2021). "Collectively, m6A RNA methylation regulators KIAA1429, METTL16, METTL3, IGF2BP2, and YTHDF, and targets NASP, TIMP1, U2AF2, COL18A1, and VEGFA could serve as oncogenes in glioma, while PHLPP2 is a tumor suppressor." (PMID 34589481, 2021). "In glioma, METTL3 may also promote temozolomide resistance through m6A-mediated stabilization of SOX2, which mediates glioma stem cell formation, as METTL3 knockdown increased temozolomide sensitivity in this context." (PMID 33669361, 2021). "To investigate the effect of YTHDF2 on the malignant phenotype of glioma via m6A modification in vivo, we injected luciferase-labeled U87 cells expressing an empty vector, a YTHDF2 overexpression vector, or a METTL3 overexpression vector into the brains of nude mice." (PMID 34246306, 2021). "Notably, m6A writers METTL3, METTL16, and KIAA1429 exhibited a cross-talk with the m6A reader YTHDF1 in gliomas, GBM, and LGG." (PMID 34589481, 2021). "Our study established and validated a seven-gene signature comprising METTL3, COL18A1, NASP, PHLPP2, TIMP1, U2AF2, and VEGFA, with a good capability for predicting glioma survival, which may guide therapeutic customization and clinical decision-making." (PMID 34589481, 2021). "In conclusion, m6A RNA methylation regulators KIAA1429, METTL16, METTL3, IGF2BP2, and YTHDF1, as well as their targets may play a critical role in the occurrence of glioma, which may be beneficial to therapeutic customization and clinical decision-making." (PMID 34589481, 2021).
glioma (continued). "We then speculated that METTL3, METTL14, and YTHDC1 might affect the proliferation of glioma cells through VPS25." (PMID 34863175, 2021). "To further validate the existence of m6A modification on UBXN1 mRNA in gliomas, we performed MeRIP-sequencing of U87 cells with or without METTL3 knockdown." (PMID 34246306, 2021). "Moreover, METTL3 expression is positively associated with a higher malignant grade and poorer prognosis in IDH-wild-type gliomas but not in IDH-mutant gliomas." (PMID 40469294, 2025). "Some bioinformatics studies have also revealed that high expression of METTL3 in glioma tissues can activate multiple oncogenic pathways and upregulate the expression of oncogenic factors, including those in the Notch pathway and NOTCH3, thereby promoting the onset of gliomas." (PMID 40469294, 2025). "The regulatory function of METTL3 in lncRNAs AS in gliomas has not been previously documented." (PMID 38405130, 2024). "Additionally, m6A writer METTL3 correlates with poor OS in IDH-wildtype but not in IDH-mutant gliomas." (PMID 38071304, 2023). "Furthermore, METTL3 promotes the development and self-renewal of GSCs by increasing the expression of stem-cell-specific marker (stage-specific embryonic antigen-1, SSEA1) and glioma reprogramming factors (POU3F2, OLIG2, SALL2, and SOX2)." (PMID 38072944, 2023). "Furthermore, METTL3, FTO, and YTHDC1 were higher in IDH-mutant LGG and GBM than in wild-type gliomas; however, this did not mean that the RNA was more or less methylated (more than m6A/m5C) in IDHm gliomas." (PMID 37964279, 2023). "Moreover, METTL3-mediated m6A modification may increase LINC01003 expression and function in glioma cells." (PMID 37270527, 2023). "Interestingly, the latest research reported that METTL3 expression is positively associated with a higher grade and poorer prognosis of isocitrate dehydrogenase (IDH)-wildtype glioma but not IDH-mutant glioma." (PMID 35625706, 2022). "However, the mechanism of METTL3-mediated m6A modification on circDLC1 in glioma has not been investigated before." (PMID 35474040, 2022). "METTL3 can activate Notch pathway and facilitate glioma occurrence through regulating its direct targets NOTCH3, DLL3, and HES1, and Notch pathway genes may serve as the potential treatment targets for glioma." (PMID 34589481, 2021). "However, the protein level of VPS25 was not affected in glioma cells with KD of METTL3 or METTL14, but it was upregulated in the YTHDC1 KD cells." (PMID 34863175, 2021). "As is visible in the violin plot, the mRNA expression levels of YTHDF2, YTHDF1, METTL3, RBM15 and HNRNPC were up‐regulated in glioma compared to normal tissues, whereas the expression levels of ALKBH5, WTAP, YTHDC2, ZC3H13 and METTL14, especially of FTO, were decreased in glioma." (PMID 32449290, 2020). "The significant overlapping pathways between METTL3 and METTL14 include Glioma (20 mDrGenes in KD-METTL3, pBonferroni = 1.37×10−6, 13 mDrGenes in KD-METTL14, pBonferroni = 1.85×10−3), suggesting that these mDrGenes may be used as biomarkers of glioma." (PMID 28027310, 2016). "From other findings and our cell experiment results, we demonstrated that METTL3 can activate Notch pathway and facilitate glioma occurrence through regulating its direct targets NOTCH3, DLL3, and HES1, and Notch pathway genes may serve as the potential treatment targets for glioma." (PMID 34589481, 2021). "Collectively, these findings and other previous report demonstrated that METTL3 can activate Notch pathway and facilitate glioma occurrence through regulating its direct targets NOTCH3, DLL3, and HES1, and Notch pathway genes may serve as the potential treatment targets for glioma." (PMID 34589481, 2021). "The TMA data revealed that METTL3 protein levels were significantly elevated in high-grade gliomas (WHO grades III and IV) compared to low-grade gliomas (WHO grade II) and non-tumor brain tissue." (PMID 41321637, 2025).
glioma (continued). "The m6A quantitative analysis showed that the METTL3 and METTL14 KD decreased the total m6A modification level in glioma cells, whereas the YTHDC1 KD did not." (PMID 34863175, 2021). "We noticed that the expression of both METTL3 and METTL14 were not correlated with the WHO grade of gliomas." (PMID 30810537, 2019). "Moreover, the expression of METTL3 was positively correlated with a higher malignancy grade and grim prognosis in IDH-wild-type gliomas but not with IDH-mutant gliomas." (PMID 37964279, 2023). "However, the clinicopathological effects of METTL3-mediated RNA m6A modification and the related mechanisms of TMZ resistance in glioma have not been elucidated." (PMID 34336690, 2021). "Unlike METTL3, which only increases with grade in IDH-wildtype gliomas, we demonstrated that YTHDF2 increased along with increasing WHO grades in both IDH-mutant and IDH-wildtype gliomas." (PMID 34246306, 2021).